TRAJ33 (T cell receptor alpha joining 33)
Gene: T-cell receptor joining (J) gene on chromosome 14 (22,508,602 to 22,508,658, forward strand). Ensembl gene ENSG00000211856.
Diseases named in the same sentence as TRAJ33 in open-access papers:
TRAJ33 is named in the same sentence as 6 diseases in open-access papers, as found by Europe PMC text mining. Sharing a sentence is not in itself a finding about the gene and the disease. The quoted sentences say what the papers report.
COVID-19 (1 paper, 2022). A disease caused by infection with severe acute respiratory syndrome coronavirus 2. "Hospitalized COVID-19 and sepsis cases displayed reductions in the percentage of repertoire occupied by TRAV10, specific to invariant NK T cells, and TRAV1-2 and TRAJ33 usage, in keeping with reductions in MAIT cells." (PMID 35216673, 2022).
HIV-1 infection (1 paper, 2022). The type species of lentivirus and the etiologic agent of acquired immunodeficiency syndrome (AIDS). "The V-J gene pair TRAV1-2/TRAJ33, the only commonly used paired V-J gene in the HDs, was decreased after HIV-1 infection." (PMID 35351857, 2022).
infection (3 papers, 2019 to 2025). The state of being infected such as from the introduction of a foreign agent such as serum, vaccine, antigenic substance or organism. "Several common TRA and TRB pairs, such as TRAV1-2/TRAJ33, TRAV21/TRAJ49, TRBV6-4/TRBD2/TRBJ2-3, and TRBV5-1/TRBD1/TRBJ2-7, were consistently detected from the primary infection (PI) through the convalescent phase (HC) and into the reinfection phase (RI)." (PMID 41209021, 2025). "Briefly, WT, Traj33 KO and MR1 KO mice were intranasally inoculated with 105 colony-forming units of L. longbeachae and the lungs were harvested 7 days post-infection." (PMID 31113973, 2019).
cancer (1 paper, 2020). A tumor composed of atypical neoplastic, often pleomorphic cells that invade other tissues. "Within all the three tissue compartments examined for each of the three cancer types, TRAJ33 was the most commonly used Jα segment whereas TRAJ12 and TRAJ20 were detectable only in a minority of MAIT cells." (PMID 32849590, 2020). "Our examination of the TCR repertoire of MAIT cells validated their preferential usage of TRAJ33 in the blood, normal tissues and tumors across the three cancer types." (PMID 32849590, 2020).
TRAJ33 also shares sentences with these, for which no sentence is quoted: Erythema (1 paper); Sepsis (1).